HAMP (hepcidin antimicrobial peptide)
Diseases named in the same sentence as HAMP in open-access papers (continued):
Sharing a sentence is not in itself a finding about the gene and the disease.
hereditary hemochromatosis (18 papers, 2013 to 2025). An inherited metabolic disorder characterized by iron accumulation in the tissues. "The patient in this report has type 2B hereditary hemochromatosis caused by a rare HAMP gene mutation, which is also known as juvenile hereditary hemochromatosis." (PMID 39005658, 2024). "Hereditary hemochromatosis with mutations in the HAMP gene can lead to islet autoantibody-positive type 1 diabetes." (PMID 39005658, 2024). "Hereditary hemochromatosis is a known iron loading disorder due to HAMP mutations, emphasizing hepcidin's crucial role in responding to iron status." (PMID 38555503, 2024). "Mutations in hepcidin antimicrobial peptide (HAMP), the hepcidin encoding gene, lead to strongly decreased hepcidin levels and a severe juvenile form of the iron storage disorder hereditary hemochromatosis (HH), but HAMP mutations are very rare." (PMID 27846281, 2016). "Moreover, hereditary hemochromatosis can be produced by other mutations in iron-modulating genes, such as hemojuvelin, hepcidin antimicrobial peptide (HAMP), transferrin receptor-2, ferroportin, ceruloplasmin and transferrin." (PMID 31083351, 2019). "In hereditary hemochromatosis, mutations in genes such as HFE, HJV, TFR2, and HAMP result in inappropriately low hepcidin levels, leading to uncontrolled iron absorption and subsequent systemic overload." (PMID 40872603, 2025). "Compared with hereditary hemochromatosis caused by HFE and TFR2, HAMP gene mutation has a greater risk of heart attack, skin changes, liver fibrosis, and hypogonadism." (PMID 39005658, 2024). "Third, it is known that mutations in several genes such as HFE, Hjv, HAMP and FPN result in hereditary hemochromatosis (HH), a disorder that causes excess high iron absorption." (PMID 27099954, 2016). "Other types of hereditary hemochromatosis are caused by mutations in the transferrin receptor-2 gene (TfR2), hemojuvelin gene (HJV), hepcidin gene (HAMP), and the ferroportin gene (SCL40A1)." (PMID 28270766, 2017). "Mutations of transferrin receptor-2 gene (TfR2), hemojuvelin gene (HJV), hepcidin gene (HAMP) and the ferroportin gene (SCL40A1) contribute to less frequent forms of hereditary hemochromatosis." (PMID 30340370, 2018). "A liver biopsy showed an almost normal liver specimen with a slight deposition of iron in 2-3% of hepatocytes, and a genetic examination of hereditary hemochromatosis revealed no typical mutations in HFE, TFR2, HJV, HAMP, or SLC40A1." (PMID 36968338, 2023). "No mutations in genes associated with hereditary hemochromatosis (HFE, HJV, HAMP, TFR2, and SLC40A1) were found." (PMID 36309641, 2022). "Other types of hereditary hemochromatosis are rare and broadly defined as non-HFE hereditary hemochromatosis and include mutations in the hemojuvelin gene, hepcidin (HAMP gene), transferrin receptor 2 gene, and ferroportin gene." (PMID 32641120, 2020).
juvenile hemochromatosis (11 papers, 2009 to 2025). "Type 2 HH, known as juvenile hemochromatosis, is caused by variants of the hepcidin (HAMP) and hemojuvelin (HJV) genes, while type 3 HH is related to variants of the TfR2 (TFR2) gene." (PMID 34067164, 2021). "Homozygous mutations of the gene encoding for hepcidin (HAMP) lead to rare cases of juvenile hemochromatosis." (PMID 19238200, 2009). "Hemochromatosis type 2, also defined as juvenile hemochromatosis, is divided into type 2A (mutation of the hemojuvenile gene, HJV, MIM #602390) and type 2B (mutation of the hepcidin antimicrobial peptide gene, HAMP, MIM #613313)." (PMID 27363994, 2016). "Juvenile hemochromatosis (JH) or type 2 hereditary hemochromatosis, is a rare condition affecting about 1 in 4.8 million people and results from autosomal recessive loss-of-function mutations in either the HJV (type 2a) or HAMP (type 2b) genes." (PMID 29373985, 2018). "Juvenile hemochromatosis is the name of the HH types 2a and 2b (OMIM #602390 and #613313) that are caused by mutations in the hemojuvelin (HJV) protein (coded by the HFE2 gene) and in the iron hormone hepcidin (coded by the HAMP gene) (OMIM *608374 and *606464)." (PMID 34946929, 2021).
iron deficiency (10 papers, 2013 to 2024). "FKN seems to act as a negative regulator of HAMP at less severe iron deficiency, while it notably enhances HAMP transcription at lower iron concentrations." (PMID 37373063, 2023). "First, HAMP transcription in hepatocytes is upregulated by iron loading and suppressed by iron deficiency as well as expanded or ineffective erythropoiesis." (PMID 37578340, 2023). "The upregulation of cardiac HAMP in mice fed an iron-deficient diet raises the possibility that it may be involved in protecting the heart in the setting of systemic iron deficiency." (PMID 27897970, 2016). "Likewise, other SNPs with linkage disequilibrium with analyzed variants in TF, TFR, and HAMP genes could be risk factors for iron deficiency in ASD; however, to the best of our knowledge, such analyses have not been conducted so far." (PMID 31936202, 2020). "Loss of HAMP responsiveness in the PASMCs of fpnC326Yfl/fl SMMHC-CreERT2+ mice resulted in increased FPN expression, intracellular iron deficiency, and remodelling of the pulmonary arteries, giving rise to PAH." (PMID 31152133, 2019).
liver cancer (8 papers, 2019 to 2023). An epithelial or non-epithelial malignant neoplasm that arises from the liver. "The downregulation of HAMP, as we demonstrated in HCC, was also related to liver fibrosis and cirrhosis, both important risk factors for liver cancer." (PMID 38067357, 2023). "The results showed that the expression of PAIP1 had a significant negative correlation (P < 0.05) with that of APOC3, CCL14, IL1RN, SERPINA3, and HAMP in liver cancer tissues." (PMID 37101794, 2023). "HAMP gene knockdown led to enhanced cancer cell proliferation and migration in vitro and xenograft tumor growth in vivo in liver cancer models." (PMID 34277457, 2021). "Interestingly, reduced HAMP expression—accompanied by highly methylated CpG island sites within the HAMP promoter region—has been observed in patients with liver cancer." (PMID 38034086, 2023). "In addition, HDAC inhibitors have been shown to upregulate HAMP expression in HepG2 cells, a human liver cancer cell line." (PMID 38034086, 2023). "However, HAMP was remarkably downregulated in human liver cancers, as described in our recent publication." (PMID 36532749, 2022). "Altogether, our results indicate that BMP6/HAMP insufficiency might be an important factor in liver cancer development or progression." (PMID 34277457, 2021). "Our study found that HAMP is downregulated in liver cancer and indicates poor disease prognosis." (PMID 31052210, 2019). "In this study, blocking HAMP action by its antagonist Fursultiamine moderately ameliorated Sorafenib-induced cell death, indicating that Sorafenib-induced HAMP expression might be involved in its cytotoxic effect on liver cancer cells." (PMID 34277457, 2021).
iron overload diseases (4 papers, 2014 to 2020). "It is encoded by the hepcidin antimicrobial peptide (HAMP) gene, mutations of which are connected with severe iron overload diseases and hemochromatosis." (PMID 33036384, 2020). "The control of hepcidin levels is deficient during genetic hemochromatosis related to HFE, TFR2, HJV, or HAMP mutation in humans, leading to iron-overload diseases." (PMID 24926268, 2014). "Homozygous and compound heterozygous mutations in the HAMP or HJV genes induce an early and severe iron overload disease (juvenile hemochromatosis) that is related to severe hepcidin deficiency with major complications that quickly impact well-being and life expectancy." (PMID 30486249, 2018).
liver fibrosis (4 papers, 2023 to 2024). "They reported that the overexpression of HAMP significantly improved liver fibrosis by suppressing proinflammatory response, infiltration of macrophages, and HSCs activation in a mouse model of NASH induced by a choline-deficient l-amino acid-defined (CDAA) diet." (PMID 38555503, 2024).
cardiomyopathy (3 papers, 2011 to 2023). A disease of the heart muscle or myocardium proper. "Several of the proteins impacted by myectomy (POSTN, MMP12, CDON, NAMPT, HAMP, LTA4H) were previously reported to be altered in cardiovascular disease, cardiomyopathy, or vascular disease with effects mediated through inflammatory mechanisms." (PMID 33804404, 2021).
gastric cancer (3 papers, 2021 to 2023). A primary or metastatic malignant neoplasm involving the stomach. "Since the association between EBV and hepcidin (HAMP) was also observed in EBVaGC, we performed a transcriptional analysis directed to identify the regulatory elements of HAMP expression in gastric cancer." (PMID 36675141, 2023).
prostate carcinoma (3 papers, 2018 to 2022). A carcinoma that arises from epithelial cells of the prostate gland. "The dysregulation of HAMP is correlated with prostate cancer growth and progression." (PMID 36585741, 2022). "Interestingly in prostate cancer the SOSTDC1 gene promoter is highly methylated leading to suppression of gene transcription, and this is associated with increased HAMP expression and poorer prognosis in patients with prostate tumours." (PMID 29771984, 2018). "According to recent reports, upregulated HAMP expression indicates poor cancer prognosis, including non-small cell lung and prostate cancers." (PMID 36523770, 2022).
rheumatoid arthritis (3 papers, 2013 to 2023). A chronic, systemic autoimmune disorder characterized by inflammation in the synovial membranes and articular surfaces. "Tocilizumab, a monoclonal antibody approved for several indications such as rheumatoid arthritis, giant cell vasculitis or cytokine release syndrome, targets the IL-6R and thus one of the major pathways to induce the transcription of the HAMP (for hepcidin-antimicrobial peptide) gene." (PMID 33842333, 2021).
aneurysm (2 papers, 2017 to 2023). Bulging or ballooning in an area of an artery secondary to arterial wall weakening. "In patients, plasma HAMP levels were raised and inversely correlated with aneurysm growth, suggesting a potential disease-modifying role." (PMID 36951059, 2023). "In this study, we report that both in patients and in an experimental mouse model of AAA, HAMP expression is markedly raised in smooth muscle cells (SMCs) within the aneurysm tissue." (PMID 36951059, 2023). "We found that HAMP protein was markedly abundant in the aneurysm tissue, in contrast to control vascular tissue (omental artery) from AAA patients and to abdominal aortic tissue from non-AAA controls." (PMID 36951059, 2023). "Together, these data suggest that HAMP expression in SMCs of the aneurysm wall may have a disease-modifying role." (PMID 36951059, 2023). "Relative differences in HAMP protein abundance were replicated at the mRNA level, confirming that HAMP protein present in the aneurysm tissue is the product of local gene expression rather than of endocrine source." (PMID 36951059, 2023).
beta thalassemia (2 papers, 2019 to 2020). Beta-thalassemia (BT) is characterized by deficiency (Beta+) or absence (Beta0) of synthesis of the beta globin chains of hemoglobin (Hb). "The aim of this research work was to study the presence of G71D mutation of HAMP gene and H63D mutation of HFE gene in beta thalassemia major and minor group to check the association of these mutations with serum ferritin level of beta thalassemia patients." (PMID 32588561, 2020). "The G71D and H63D mutation of HAMP and HFE gene are frequently found in beta thalassemia major patients." (PMID 32588561, 2020). "We studied the presence of G71D mutation of HAMP gene and H63D mutation of HFE gene in beta thalassemia major and minor group to check the association of these mutations with serum ferritin level of beta thalassemia patients." (PMID 32588561, 2020).
breast carcinoma (2 papers, 2022 to 2023). "For example, GDF15 knockdown strongly suppresses HAMP mRNA (encoding hepcidin protein) in 3D culture but does not affect HAMP transcription in the 2D culture of an MCF-7 (breast carcinoma) cell line." (PMID 37296952, 2023).
Cirrhosis (2 papers, 2022 to 2023). A chronic disorder of the liver in which liver tissue becomes scarred and is partially replaced by regenerative nodules and fibrotic tissue resulting in loss of liver function.
colon cancer (2 papers, 2022 to 2024). "Analysis of human colon tumor tissue revealed decreased expression of IRP-1, HMOX-1, and FTH1 but increased HAMP expression." (PMID 39097854, 2024).
colorectal adenocarcinoma (2 papers, 2013 to 2022). The most common type of colorectal carcinoma. "The forward stepwise mode constructed discriminant functions including all genes under study, and showed that DMT1, HAMP, TfR2, miR-31, miR-149, miR-182, miR-194 were the most significant parameters responsible for progression of colorectal adenocarcinoma, assigning all cases correctly (p < 0.0001)." (PMID 24078156, 2013).
lung carcinoma (2 papers, 2019 to 2022). "The polymorphism rs10421768 in HAMP may be associated with lung cancer risk, however analyses on a larger population should be performed to confirm this correlation." (PMID 30640897, 2019). "Interestingly, another recent report showed that HAMP expression was upregulated at the mRNA level in lung cancer tissues and was associated with immune infiltrations in the tumor microenvironment, indicating that HAMP might be a potential prognostic biomarker in cancers." (PMID 36532749, 2022).
lymph node metastasis (2 papers, 2022). "Increased HAMP expression in non-small-cell lung cancer tissue and serum is associated with lymph node metastasis and tumor clinical stage." (PMID 36585741, 2022). "In line with these two reports, our results from a large cohort confirmed the strong correlation of HAMP upregulation with cancer grade, tumor stage, lymph node metastasis, distal metastasis, disease progression, and patient survival." (PMID 36532749, 2022).
melanoma (2 papers, 2022 to 2024). A malignant, usually aggressive tumor composed of atypical, neoplastic melanocytes. "The genes of HAMP, SLC7A5, CYBB, and IFNG were highly expressed in melanoma cell lines, while JDP2, TUBE1, PROM2, GPX2, FBXW7, and ARNTL were lowly expressed in melanoma cell lines." (PMID 35373463, 2022).
Multiple Myeloma (2 papers, 2013 to 2022). "In fact, elevated serum HAMP levels have been associated with renal cell carcinoma metastases; as well, high urinary HAMP levels have been observed in multiple myeloma patients, both suggesting pathologic secretion of HAMP by the cancer cells." (PMID 23991213, 2013).
osteoporosis (2 papers, 2019 to 2024). A condition of reduced bone mass, with decreased cortical thickness and a decrease in the number and size of the trabeculae of cancellous bone (but normal chemical composition), resulting in increased fracture incidence. "In this study, the random forest model was used to screen out five key ferroptosis genes, including CP, HAMP, HMOX1, FLT3, and SLC2A3, and these 5 differentially expressed key ferroptosis genes were preliminarily verified in the osteoporosis model constructed." (PMID 38650009, 2024).
pancreatic cancer (2 papers, 2022 to 2023). "Surprisingly, expression of SLC40A1 is significantly higher in pancreatic tumors as compared to normal pancreas tissues in TCGA and GTEx databases, whereas HAMP expression is not differentially expressed in normal vs tumor pancreatic tissues." (PMID 36333531, 2022).
renal carcinoma (2 papers, 2025). A carcinoma arising from the epithelium of the renal parenchyma or the renal pelvis. "Regarding other candidate genes, such as HAMP and CAV1, although numerous studies have demonstrated their potential roles in RCC and their adverse effects on the prognosis of ccRCC patients, their impact on the malignant phenotype of renal cancer cells in our in vitro model was not significant." (PMID 40341358, 2025).
Salmonella Infections (2 papers, 2017 to 2021). Infections with bacteria of the genus SALMONELLA. "To understand better the role of HAMP during Salmonella infection, we next studied the impact of Salmonella infection in mice deficient in HAMP (Hamp−/−)." (PMID 28507548, 2017). "In this study, we observed a strong negative regulation of the iron exporter FPN at both the mRNA and the protein level in Hamp−/− mice, indicating that the repression of the iron exporter by Salmonella infection is independent of HAMP action." (PMID 28507548, 2017).
type 1 diabetes (2 papers, 2020 to 2024). "It was first reported that positive pancreatic islet autoantibodies diabetes onset of JHH resulted from loss‐of‐function mutations of HAMP, of which the atypical JHH should be differentially diagnosed with type 1 diabetes at the onset." (PMID 33016646, 2020).
acute cholecystitis (1 paper, 2011). "Biliary HAMP expression is stress-inducible, in that it increased after IL-6 stimulation and during acute cholecystitis." (PMID 21283681, 2011).
astrocytoma (1 paper, 2009). "We investigated the mRNA levels of hepcidin (HAMP), HFE, neogenin (NEO1), transferrin receptor 1 (TFRC), transferrin receptor 2 (TFR2), and hemojuvelin (HFE2) in normal human brain, brain tumors, and astrocytoma cell lines." (PMID 19386095, 2009).
biliary atresia (1 paper, 2017). A rare, biliary tract disease characterized by progressive obliterative cholangiopathy of the intra- and extrahepatic bile ducts, occurring in the embryonic/ perinatal period, leading to severe and persistent neonatal jaundice and acholic stool. "Moreover, as KD occurs more commonly in Asian populations than European populations, we also reported that the C allele of rs916145 in the HAMP promoter area has a higher frequency of developing biliary atresia, which is consistent with the low incidence of biliary atresia in European populations." (PMID 28881695, 2017).
brain tumors (1 paper, 2009). "The present study describes the expression of several iron-related genes including hepcidin (HAMP), HFE, neogenin(NEO1), transferrin receptor 1 (TFRC), transferrin receptor 2 (TFR2), and hemojuvelin(HFE2) in normal human brain, brain tumors, and astrocytoma cell lines." (PMID 19386095, 2009).
cardiac hypertrophy (1 paper, 2019). "In addition, it has been shown that HAMP knockout at the cardiac level leads to an increase in cardiac FPN; moreover, HAMP loss or HAMP unresponsiveness is associated to cardiac hypertrophy and apoptosis." (PMID 31049138, 2019).
cholangiocarcinoma (1 paper, 2022). A carcinoma that arises from the intrahepatic biliary tree (intrahepatic cholangiocarcinoma) or from the junction, or adjacent to the junction, of the right and left hepatic ducts (hilar cholangiocarcinoma). "In contrast, the expression level of HAMP was significantly lower in cholangiocarcinoma and liver hepatocellular carcinoma." (PMID 36585741, 2022).
cholangitis (1 paper, 2011). An acute or chronic inflammatory process affecting the biliary tract. "Furthermore, biliary prohepcidin levels positively correlate with bilirubin levels in patients with PSC-cholangitis, whereas cholestasis was shown to downregulate HAMP expression in the liver." (PMID 21283681, 2011).
chronic hepatitis (1 paper, 2020). An active inflammatory process affecting the liver for more than six months. "Considering hypermethylation at HAMP promoter in HCC, co-treatment with 4-PBA and DAAs also might be beneficial to possibly reduce the HCC risk while treating chronic hepatitis." (PMID 32752233, 2020).